ENSG00000212181
Synonyms: LOC124900532
Gene: Small nucleolar RNA gene on chromosome 2 (148,260,574 to 148,260,708, reverse strand). Ensembl gene ENSG00000212181.
Gene Ontology:
Biological process: RNA processing
Cellular component: nucleolus
Homologues: Paralogues in human: SNORA48 (84% identical), SNORA48B (81% identical).